MIR873 (microRNA 873)
Synonyms: hsa-mir-873; MIRN873; mir-873
Gene: MicroRNA gene on chromosome 9 (28,888,879 to 28,888,955, reverse strand). Ensembl gene ENSG00000215939.
Gene Ontology:
Biological process: miRNA-mediated post-transcriptional gene silencing
Cellular component: RISC complex
Homologues: Orthologues: chimpanzee ptr-mir-873 (100% identical), rabbit MIR873 (100% identical), macaque mml-mir-873 (91% identical), mouse Mir873b (66% identical), guinea pig MIR873 (65% identical).